HRNR (hornerin)
Diseases named in the same sentence as HRNR in open-access papers (continued):
Sharing a sentence is not in itself a finding about the gene and the disease.
cancer (8 papers, 2012 to 2023). A tumor composed of atypical neoplastic, often pleomorphic cells that invade other tissues. "HRNR (Hornerin) is a S100 family member that is required for epidermal barrier formation and carcinoma progression." (PMID 34815476, 2021). "As a member of the S100 protein family, the role of HRNR still remains to be fully understood, especially in cancer research." (PMID 30103712, 2018). "We have also provided evidence suggesting that HRNR signals through the AKT cascade to regulate cancer cell behavior; however, how HRNR links to AKT activation remains to be determined." (PMID 30103712, 2018). "Quantitative real-time PCR was used to determine the expression levels of hornerin in each stage of the MCF10A cancer progression model." (PMID 22727333, 2012). "Moreover, perturbed expression of hornerin possibly provides a starting point for the emergence of DDA-resistant cancer cells due to cancer-specific DDR defects, as depletion of hornerin substantially increased the survival rate of etoposide-treated cells." (PMID 37596441, 2023). "Thus, hornerin-mediated DiM, as the checkpoint in mitotic exit, is clinically relevant and could be exploited to improve therapeutic outcomes for cancer patients." (PMID 37596441, 2023). "Four proteins (KRT14, Hornerin [HRNR], Cell Division Cycle Associated 8 [CDCA8], and Fibronectin Type III Domain Containing 3B [FNDC3B]) were identified as unique to all patient HGSC cells at the cancer–mesothelial interface following this high-stringency approach." (PMID 31443478, 2019). "The potential contribution of taxifolin to HRNR, FLG2, CRCT1, KPRP and other tumor suppressor gene expressions in BC via its impact on cell metabolism is indeed intriguing, considering that metabolic alterations are a typical feature of cancer cells." (PMID 37370814, 2023). "In agreement with RT-PCR data (above), HRNR, KRT14, and CDCA8 were detected in cancer cell lysates but not in the mesothelial cell controls." (PMID 31443478, 2019).
infection (1 paper, 2019). The state of being infected such as from the introduction of a foreign agent such as serum, vaccine, antigenic substance or organism. "We therefore propose that the highly abundant protein HRNR is an important precursor for a collection of versatile local disinfectants, acting at the outermost surface of barrier organs, helping to keep healthy skin and mucosal surfaces free of infection." (PMID 30833614, 2019). "In the search for potential mechanisms underlying the remarkable resistance of healthy skin against infection by soil bacteria like Pseudomonas (P.)aeruginosa we identified fragments of the intrinsically disordered protein hornerin as potent microbicidal agents in the stratum corneum." (PMID 30833614, 2019).
neurodegenerative disease (1 paper, 2022). A disorder of the central nervous system characterized by gradual and progressive loss of neural tissue and neurologic function. "Although the expression of hornerin has been observed in many tissues, its expression in human brain sections has not been reported, and little is known about the roles of hornerin in neurodegenerative diseases." (PMID 35246273, 2022).
retinopathy (1 paper, 2024). "In GWAS analysis, we found 12 SNPs had a significant association (p < 10-4) with HCQ retinopathy in genes LCE4A, HRNR, OR2T4, NUDT17, CCDC66, PRSS3, PABPC1 and IGHV." (PMID 38548946, 2024).
HRNR also shares sentences with these, for which no sentence is quoted: breast tumor (2 papers); invasive lobular carcinomas (2); actinic keratosis (1); atherosclerosis (1); autoimmune liver diseases (1); cholesteatoma (1); Cirrhosis (1); Darier disease (1); epidermolytic ichthyosis (1); genetic diseases (1); gynecological cancer (1); hay fever (1); hepatitis B (1); Hyperkeratosis (1); ichthyosis vulgaris (1); lichen planus (1); liver cancer (1); liver failure (1); mantle cell lymphoma (1); prostate carcinoma (1); seborrheic keratosis (1); sensitization (1); thymoma (1).